CXCL10 (C-X-C motif chemokine ligand 10)
Diseases named in the same sentence as CXCL10 in open-access papers (continued):
Sharing a sentence is not in itself a finding about the gene and the disease.
Crohn disease (15 papers, 2005 to 2025). A gastrointestinal disorder characterized by chronic inflammation involving all layers of the intestinal wall, noncaseating granulomas affecting the intestinal wall and regional lymph nodes, and transmural fibrosis. "In a Crohn’s disease model, CXCL10 blockade reduces serum IL-12p40, IL-2, IFN-γ, IL-1α, IL-1β, and TNF-α." (PMID 29910805, 2018). "It has been suggested that atorvastatin to reduce plasma CXCL10 levels may be a candidate for future treatment of Crohn’s disease." (PMID 36118873, 2022). "Fenofibrate is another therapy that may reduce CXCL10 activity and is hypothesized to have therapeutic activity in inflammatory diseases like Crohn’s disease." (PMID 34582497, 2021). "Furthermore, statin medications commonly used for cholesterol control have been shown to decrease CXCL10 and to be effective in CXCL10-mediated Crohn's disease." (PMID 29768624, 2018). "Hence the reduction of plasma CXCL10 levels by atorvastatin may represent a candidate for an approach to the treatment of Crohns disease in the future." (PMID 19421322, 2009). "After verifying COL1A1, CXCL10, MMP2 and FGF2 in samples from CD patients, to further verify the expression of these four genes in Crohn’s disease fibrosis, we prepared a rat model of CD fibrosis using TNBS." (PMID 37622114, 2023). "Colocalization suggested neither a common causal SNP for IP10 (CXCL10) and AD (PP.H4 = 0.09), nor for IP10 (CXCL10) and Crohn disease (PP.H4 = 0.09; eFigure 9)." (PMID 36384659, 2023).
injury (15 papers, 2008 to 2025). Damage inflicted on the body as the direct or indirect result of an external force, with or without disruption of structural continuity. "Very recently, the same group reported increased BAL levels of CXCL9 and CXCL10 in a prospective multicenter study during episodes of acute rejection and acute lung injury in the first year post-LTx, which form known risk factors for future CLAD development." (PMID 34122421, 2021). "It is well known that hepatic CXCL-10 expression is increased in experimental models of Con A induced liver injury and associated with the migration of T lymphocytes." (PMID 24808635, 2014). "Next, we tested if Cxcl10 is mechanistically important in alveolarization and cell survival during acute hyperoxia-induced neonatal lung injury." (PMID 37876024, 2023). "C-X-C motif chemokine 10 (CXCL10) promotes liver inflammation in chronic or acute liver injury by recruiting and activating immune cells such as B-lymphocytes, T-lymphocytes and dendritic cells." (PMID 37122694, 2023). "CXCL10/IP-10 (IFNγ-inducible protein 10) and CXCL9/Mig (monokine induced by IFN-γ) are up-regulated in CS-induced lung injury and may attract T-cell recruitment to the lung." (PMID 19087279, 2008).
kidney transplant (15 papers, 2009 to 2026). A surgical procedure in which one or both kidneys from a donor are implanted into a recipient. "During kidney transplant rejection intrarenal RNA expression of Th1-associated ligands CXCL10 and CCL5 have been documented, also increased urinary chemokines CXCL9 and CXCL10 were found during acute rejection compared to stable recipients." (PMID 23717673, 2013). "In a previous study on kidney transplant recipients, our group identified miR155-5p and interferon gamma inducible chemokine 10 (CXCL-10) as prognostic and diagnostic biomarkers of rejection based on a receiver operating characteristic (ROC) curve data analysis." (PMID 33481955, 2021). "In kidney transplant recipients, urinary CXCL10 levels increase during antibody-mediated rejection that is accompanied by microvascular inflammation." (PMID 35657798, 2022). "Our results indicated CXCL10 as an important mediator involved in inflammatory infiltration and pain symptoms of prostatitis by promoting the migration of macrophages and secretion of inflammatory mediators via CXCR3-mediated ERK and p38 MAPK activation." (PMID 34659199, 2021). "During pathologic progression of prostatitis, prostatic stromal cells and infiltrating leukocytes can also serve as the source of CXCL10, forming a positive feedback loop to amplify inflammation." (PMID 34659199, 2021). "Th1 cells preferentially express the chemokine receptors CCR5 and CXCR3 migrating towards CCL5 and CXCL10 which are expressed by TECs and present during kidney transplant rejection." (PMID 23717673, 2013). "This study aimed to develop a logistic regression model to investigate whether urinary miR155-5p pellet expression and urinary CXCL-10 concentration may predict the probability of rejection in adult kidney transplant recipients." (PMID 33481955, 2021). "Our results identify CXCL10 as an important mediator of prostatitis involved in inflammatory infiltration and pain symptoms, which could serve as a potential therapeutic target and diagnostic marker for CP/CPPS." (PMID 34659199, 2021). "While the specific role of ATF3 (activating transcription factor 3) in the suppression of PCa with PTEN (phosphatase and tensin homolog) dysfunction is meanwhile well known, the tumor suppressor function of IGF1, CXCL10, HIF1A, CXCL8, and CSF1 in prostate carcinogenesis remains to be elucidated." (PMID 36321189, 2023). "The literature review presented here suggests that NGAL, KIM-1, CXCL-10, CysC, OPN, and CLU may become essential markers in predicting allogeneic kidney transplant rejection." (PMID 35669103, 2022). "In summary we suggest CXCL9 (but not CXCL10) testing in urine as an adjunct test to immunodominant DSA characterization in serum for the prediction of late antibody-mediated rejection in clinically well-presenting, but DSA-positive long-term kidney transplant patients." (PMID 32328494, 2020). "Furthermore, diminished CXCL-10 and renin, as well as non-significant trends towards decreased biomarker concentrations for KIM-1, TIMP-1, and osteopontin were noted after CEF and PTX treatment, suggesting that addition of PTX to antibiotics may reduce acute kidney injury during neonatal sepsis." (PMID 39963236, 2024).
leukemia (15 papers, 2011 to 2026). A malignant (clonal) hematologic disorder, involving hematopoietic stem cells and characterized by the presence of primitive or atypical myeloid or lymphoid cells in the bone marrow and the blood. "Our studies demonstrate that meningeal stromal cells, specifically pericytes and fibroblasts, induce CXCL10 expression in response to leukemia and that loss of CXCL10 attenuated T-ALL influx into the meninges." (PMID 41129238, 2026). "Although we did not directly investigate the upstream mechanisms regulating CXCL10 induction in this study, our findings of reduced IFN-γ, TNF-α, and IL-27 expression in leukemia-bearing CXCL10-deficient mice underscore the need for further mechanistic studies." (PMID 41129238, 2026). "The results showed significant reductions in TGF-β1, CXCL12, CXCL10, OPN, and COX-2, of which COX-2 and OPN have been shown to be associated with promoting leukemia progression, and CXCL12, TGF-β1, and CXCL10 have been reported to be associated with leukemia resistance." (PMID 40121502, 2025). "Although targeting CXCL10 in the CSF for leukemia treatment constitutes an ongoing research focus, it potentially opens new avenues for future therapeutic interventions." (PMID 41129238, 2026). "CXCL10 is also active in B cell lymphoma and leukemia and high circulating concentrations predict unfavorable clinical outcomes." (PMID 39452756, 2024). "Gene-profiling experiments showed that treating human leukemia HL-60 cells with Dip G was associated with a remarkable upregulation of STAT1 target gene expression, including IFIT3 and CXCL10." (PMID 28471454, 2017). "Furthermore, we observed an enhanced inflammatory response in the CSF of leukemia-bearing mice characterized by elevated CXCL10 levels and reduced proliferation of leukemic cells in the meninges compared with the BM." (PMID 41129238, 2026). "Also in AML, in an experimental study, it was observed that the expression of the CXCL-10 gene (involved in angiogenesis) was increased in selected leukemia cell lines." (PMID 39996769, 2025). "Furthermore, CXCL10 was shown to promote leukemia cell survival and drug resistance by enabling cells to evade apoptosis induced by chemotherapeutic agents like cytarabine and methotrexate." (PMID 40121502, 2025). "The delivery of various transgenes that may antagonize immunoevasion mechanisms, such as the chemokine CXCL10, which activates NK cells to kill B7-H1-overexpressing dormant leukemia cells, could help the host in the clearance of the cancer cells." (PMID 21884581, 2011). "Additionally, based on the role of CXCL10 on inhibition of neovascularization may indirectly decrease the complications of leukemia and BMT in the patient, leading to a better prognosis." (PMID 34711015, 2021). "To further investigate how CXCL10 regulates T-ALL infiltration into the meninges, we analyzed leukemia burden and CXCL10 levels in the BM, meninges, and other organs at various time points during ΔE-NOTCH1-driven T-ALL development." (PMID 41129238, 2026). "Res and ω-3 PUFA reduced IL-1β, IL-6, TNF-α, CXCL10/IP-10, CCL13/MCP-4 and CCL20/MIP-3α in LPS/IFN-γ activated human leukaemia THP-1 cells, which is indicative of a dampening effect on M1 macrophages." (PMID 35884829, 2022). "In leukemia, this was observed in a study involving pediatric patients with ALL, with CXCL10 inducing chemotaxis of leukemic cells that expressed CXCR3, and also decreased chemotherapy-induced apoptosis in the leukemic cells CXCR3+." (PMID 34335758, 2021). "The chemokine-receptor axes play parts in development of leukemia, CXCL1, CXCL10 and CXCL12 are involved in immune responses." (PMID 34711015, 2021). "As we know, CXCR3’s ligands included CXCL10 (IP-10) and CXCL11 (I-TAC), and few researches about CXCL9.CXCL10 was selected through stimulating leukemia U937cell lines from the DNA pool by Luster who comes from American." (PMID 30973890, 2019).
leukemia (continued). "Moreover, we report that leukemia-derived proinflammatory cytokines, TNF-α, IL-27, and IFN-γ, induced CXCL10 in the meningeal stroma." (PMID 41129238, 2026). "Furthermore, we discovered elevated levels of CXCL10, a CXCR3 ligand, in the cerebrospinal fluid from patients with T-ALL and leukemia-bearing mice." (PMID 41129238, 2026). "Therefore, as a future work the designing of leukemia animal models with employing recombinant CXC chemokines CXCL1, CXCL10 and CXCL12 is proposed for the examination of the role and ability of these chemokines in control of AML complications." (PMID 34711015, 2021). "T-ALL cells gradually increased in the BM of leukemia-bearing mice, independent of CXCL10 knockout." (PMID 41129238, 2026).
non-small cell lung carcinoma (15 papers, 2020 to 2025). A group of at least three distinct histological types of lung cancer, including non-small cell squamous cell carcinoma, adenocarcinoma, and large cell carcinoma. "ALKBH5 promotes non-small cell lung cancer progression by regulating cancer and tumor-associated macrophage behavior through the JAK2/p-STAT3 pathway and the expression of CCL2 and CXCL10, respectively." (PMID 38872221, 2024). "Moreover, CXCL10 is considered to inhibit non-small-cell lung carcinoma tumor growth and metastasis by disturbing tumor angiogenesis." (PMID 38891915, 2024). "Finally, elevated pre-treatment CXCL9 and CXCL10 levels appear to correlate with the response to anti-PD1 therapy in patients with non-small cell lung cancer." (PMID 37569757, 2023). "IGF2BPs, as functional downstream modulators of circNDUFB2, regulate the secretion of CXCL10, CXCL11, CCL5, and IFNβ in non-small cell lung cancer (NSCLC)." (PMID 36225914, 2022). "Also, high expression of CXCL10 and other CXCR3 ligands in ovarian, esophageal, and non-small cell lung carcinoma indicate favorable prognoses." (PMID 34328416, 2021).
thyroid cancer (15 papers, 2015 to 2024). "In thyroid cancer, high CXCL10 expression is associated with increased tumor infiltration of immune cells including CD8+ T cells, which predicts better patient OS." (PMID 35207629, 2022). "A mouse xenograft study has suggested histamine, CXCL1/GRO-α and CXCL10/IP-10 as TMC secreting factors that are important in thyroid cancer cell proliferation." (PMID 36293435, 2022). "Histamine, IL-6, IL-1, TNF-α, and chemokines such as CXCL1/GRO-α, CXCL8/IL-8, and CXCL10/IP-10 are secreted from mast cells when thyroid cancer cells are activated." (PMID 36293435, 2022). "The potential kinase targets of CXCL10 in thyroid carcinoma were analyzed using the LinkedOmics database." (PMID 33345267, 2021). "This is because on the one hand, it could secrete histamine, CXCL1/GRO-α and CXCL10/IP-10 to promote the proliferation of thyroid cancer cells, and on the other hand, it could initiate EMT by secreting TNF, IL-6 and CXCL8/IL-8, which were essential in EMT process." (PMID 36568979, 2022). "Moreover, mast-cell-derived mediators: histamine, CXCL1 and CXCL10 could increase thyroid cancer cell survival and DNA synthesis in vitro." (PMID 30808413, 2019). "Subsequently, TCGA database results showed the expression of CXCL10, CD40LG, KRT14, TRAT1, and TREM2, with only TREM2 expression levels being upregulated in thyroid cancer." (PMID 36438899, 2022). "As for TME-related genes in thyroid cancer, a previous study has identified 30 hub genes by constructing the PPI network and set CXCL10 as the top hub gene." (PMID 36590308, 2022). "Subsequently, the TCGA database results showed the expression of CXCL10, CD40LG, KRT14, TRAT1, and TREM2, with only TREM2 expression levels being upregulated in thyroid cancer (P < 0.05)." (PMID 36438899, 2022). "The genes related to CXCL10 and differentially expressed in PTC were investigated via LinkedOmics to establish the specific mechanisms of action of CXCL10 in thyroid cancer." (PMID 33345267, 2021). "It has been also shown that histamine and chemokines (CXCL1/GRO-α, CXCL10/IP-10, and CXCL8/IL-8) released by activated human MCs modulate proliferation, survival, and invasion of thyroid cancer cells through the involvement of specific receptors." (PMID 27732965, 2016). "MCs also produce a broad spectrum of chemokines (CXCL8/IL-8, CCL25/TECK, CXCL10/IP-10, CXCL1/GRO-α), interleukins (IL-6), and other molecules (TNF-α) that are involved in the epithelial-to-mesenchymal transition (EMT) activation of thyroid cancer cells." (PMID 34204889, 2021). "Since IFN-γ induces the secretion of CXCR3 ligands and CXCL10 in normal and PTC thyrocytes, it has been proposed that CXCR3 chemokines may promote thyroid malignant transformation and/or thyroid cancer progression." (PMID 29416784, 2018).
bladder cancer (14 papers, 2015 to 2025). "This also indicates the close relationship between CXCL10 and the immune microenvironment of bladder cancer (BLCA)." (PMID 38720149, 2024). "Intriguingly, blockade of PGE2 synthesis has been shown to increase the expression of CXCL9 and CXCL10 in murine models of cutaneous melanoma, as well as our murine bladder cancer models (unpublished observations)." (PMID 35347124, 2022). "In addition, we verified the expression of CXCL10 in different human bladder cancer cells by qRT‐PCR." (PMID 38720149, 2024). "In addition, CXCL10 was found to be released in large amounts in CD14+ cells after BCG induction therapy in bladder cancer patients." (PMID 36131933, 2022). "CXCL10 may play an important role in regulating immune cell migration, differentiation, and activation in bladder cancer." (PMID 31929742, 2020). "Furthermore, chemokines CCL2 and CXCL10, which contribute to immunosurveillance, were induced by shRNAs of PPARγ and RXRα in HT-1197 bladder cancer cells bearing endogenous RXRαS427F." (PMID 28740126, 2017). "From the human data, the urine of bladder cancer patients had significantly upregulated levels of CCL2, IL-6, CXCL10, IL-1b, IFN-g, TGF-b, and IL-8 in comparison to the healthy donors." (PMID 37901214, 2023). "In comparison to healthy donors, CCL2, IL-6, CXCL10, IL-1b, IFN-g, TGF-b, and IL-8 were enriched within the urine of bladder cancer patients." (PMID 37901214, 2023). "Expression of the CXC subfamily chemokines (CXCL9, CXCL10, and CXCL13) and of the CC subfamily chemokine CCL18 was consistently found to be higher in bladder cancer patients in the CLR-high group than in the patients in CLR-low group." (PMID 36131933, 2022). "In accordance with the data from our bladder cancer explant cultures, BCG alone was completely ineffective in promoting CXCL10 secretion in such cell cultures." (PMID 25806105, 2015). "Bladder cancer tissues spontaneously expressed high levels of the granulocyte/MDSC-attractant CXCL8 and Treg-attractant CCL22, but only marginal levels of the CTL-attracting chemokines: CCL5, CXCL9 and CXCL10." (PMID 25806105, 2015). "Unexpectedly, we observed that, while BCG strongly up regulated the secretion of CXCL8 (P < 0.05) and CCL22 (P < 0.05) by ex vivo-treated bladder cancer explants (n = 11 patients), it did not enhance CXCL10 secretion." (PMID 25806105, 2015). "Our current data is consistent with the previous observations that bladder cancer tissues do not produce the desirable chemokine CXCL10 within the first week of BCG treatment, although can produce this factor after 3 weekly doses of BCG." (PMID 25806105, 2015). "However, the exact role of CXCL10, a chemokine, in bladder cancer (BLCA) is still not fully elucidated." (PMID 38720149, 2024). "In aggregate, these data, especially the prolonged increase in IP10 production observed seven days after the instillation, suggests that CXCL10, along with other pro-inflammatory cytokines, might be a useful biomarker for the classification of BCG-treated bladder cancer patients." (PMID 31277459, 2019). "By means of a 34‐cytokine and chemokine immunoassay panel, we revealed that chemokines including CCL3, CCL4, CCL5, CXCL9, and CXCL10, are robust negative correlated with expression of BCAT2 in human and murine bladder cancer cell." (PMID 36642843, 2023).